PCDH15 (protocadherin related 15)
Diseases named in the same sentence as PCDH15 in open-access papers (continued):
Sharing a sentence is not in itself a finding about the gene and the disease.
pituitary adenomas (1 paper, 2022). "In conclusion, our data suggest that the CDK8 rs17083838 variant, and possibly the PCDH15 rs10763170 variant, may increase susceptibility to sporadic pituitary adenomas in the Portuguese population." (PMID 36233050, 2022). "The aim of this study was to investigate whether the NEBL rs2359536, PCDH15 rs10763170 and CDK8 rs17083838 SNPs are associated with the susceptibility to sporadic pituitary adenomas in the Portuguese population." (PMID 36233050, 2022). "Three common variants at the NEBL (rs2359536), PCDH15 (rs10763170) and CDK8 (rs17083838) loci were previously associated with sporadic pituitary adenomas in the Han Chinese population, but these findings have not yet been replicated in any other population." (PMID 36233050, 2022).
pituitary tumor (1 paper, 2022). A benign or malignant neoplasm affecting the pituitary gland. "Most importantly, PCDH15 has been shown to interact with cadherin-related 23 (CDH23), which has been implicated in sporadic and familial forms of pituitary tumors." (PMID 36233050, 2022).
prostate carcinoma (1 paper, 2023). A carcinoma that arises from epithelial cells of the prostate gland. "We observed enrichment of mutations in several genes including understudied genes such as EYA1, CSMD3, FLT4, NCOR2, and PCDH15 and found that mutations in EYA1 and CSMD3 are associated with a poor outcome in prostate cancer." (PMID 38067373, 2023). "The association of FLT4 and PCDH15 with prostate cancer metastases has not been previously reported." (PMID 38067373, 2023). "Future directions for this work include further characterization of EYA1, CSMD3, FGFR3, and PCDH15 in prostate cancer metastases and the roles of oxidative phosphorylation and FGFR3 in prostate cancer health disparities." (PMID 38067373, 2023).
prostate tumors (1 paper, 2023). "Integrative genomic analysis of primary prostate tumors and associated LNM demonstrated the enrichment of mutations in several genes including both well-established oncogenes and tumor suppressors and understudied genes such as EYA1, CSMD3, FLT4, NCOR2, and PCDH15." (PMID 38067373, 2023).
sebaceous carcinoma (1 paper, 2023). "Somatic mutation of PCDH15 has been associated with metastasis in ocular adnexal sebaceous carcinoma." (PMID 38067373, 2023).
sebaceous gland cancer of the (1 paper, 2025). "Furthermore, metastatic adnexal sebaceous gland cancer of the eye is discovered to have a substantial mutation in PCDH15." (PMID 40686517, 2025).
Skin-Melanoma (1 paper, 2025). "In Thy-AdenoCA, the genes NRXN3 and LRP1B exceeded this threshold, as well as PCDH15 in Eso-AdenoCA and Skin-Melanoma." (PMID 40507213, 2025).
somatotrophinomas (1 paper, 2022). "In the analysis based on tumor subtype, the PCDH15 rs10763170 minor allele (T allele) was associated with somatotrophinomas under a dominant inheritance model (OR 1.55, 95% CI 1.02–2.35, p = 0.035); however, this association was no longer significant after applying the Bonferroni correction." (PMID 36233050, 2022). "However, the PCDH15 rs10763170 minor allele (T allele) presented a near-significant association with somatotrophinomas (dominant inheritance model, OR 1.55, 95% CI 1.02–2.35, p = 0.035)." (PMID 36233050, 2022).
tumor (7 papers, 2013 to 2023). "Single nucleotide polymorphism (SNP) was responsible for such variants, and single nucleotide variants (SNVs) mostly occurred as C > A and C > T. However, the role of PCDH15, MUC17, RPIL1, DAMTS12, and PAPPA219 expressed in a tumor microenvironment remains to be studied." (PMID 36147496, 2022). "A heatmap of the 110 CpGs shows overall lower methylation of these CpGs in tumors compared to adjacent non-tumor tissues: the top five hypermethylated genes were GLRX, WNT9B, SEPT9, KIAA00284, and PPYR1, and the top five hypomethylated genes were KIAA0748, PAEP, PCDH15, PTPRN2, and DUSP27." (PMID 34635168, 2021).
psychiatric disorder (5 papers, 2014 to 2024). A disorder characterized by behavioral and/or psychological abnormalities, often accompanied by physical symptoms. "Via a whole-genome analysis targeting Japanese patients with psychiatric disorders, such as BD, we identified multiple patients with a loss of the protein-coating-encoding region of the PCDH15 gene." (PMID 38806495, 2024). "A recent genome-wide association study suggested that PCDH15 is associated with psychiatric disorders." (PMID 31540999, 2019). "Furthermore, recent GWAS meta-analysis suggests a significant association between PCDH15 SNP variants and personality traits in psychiatric disorders." (PMID 32033412, 2020). "In the future, as more comprehensive genomic analysis data of patients with psychiatric disorders, including BD, becomes available, there is a sufficient possibility that the genetic association between the PCDH15 variants and onset could become statistically significant from a genetic standpoint." (PMID 38806495, 2024). "In this study, we demonstrated that Pcdh15-deletion mice display traits consistent with construct and surface validities, rendering them reliable models for the investigation of psychiatric disorders such as BD." (PMID 38806495, 2024). "In this study, we evaluated the behavioral phenotype of Pcdh15-deletion mice to establish face validity, ensuring the appropriateness of the model for investigating the mechanisms linking Pcdh15 deletion to psychiatric disorders such as BD." (PMID 38806495, 2024). "Unsurprisingly, there is limited knowledge of the relationship between the pathogenesis of BD and other psychiatric disorders and their relationship with PCDH15." (PMID 38806495, 2024). "This was accomplished through the targeted deletion of Pcdh15, a gene recognized in patients with psychiatric disorders." (PMID 38806495, 2024). "Animal models, such as the Pcdh15-deletion mice, are crucial for understanding the genetic factors responsible for the development of psychiatric disorders." (PMID 38806495, 2024). "The consistent dysfunction of the amygdala implies that Pcdh15-deletion mice may also satisfy surface validity as a model of psychiatric disorders in terms of brain function." (PMID 38806495, 2024). "Consequently, Pcdh15-deletion mice appear to be a promising model for psychiatric disorders, satisfying both construct and face validity criteria." (PMID 38806495, 2024). "Therefore, Pcdh15-deletion mice can be a novel model for BD with mania and other psychiatric disorders, with a strong genetic component that satisfies both construct and surface validity." (PMID 38806495, 2024). "Considering these findings, Pcdh15-deletion mice emerge as a potentially valuable model, meeting both construct and surface validity criteria, for investigating the mechanisms linking PCDH15 deletion to psychiatric disorders, notably BD with mania." (PMID 38806495, 2024). "This suggests that PCDH15 may play a pivotal role in various aspects of synaptic functions, and the misspliced Pcdh15 may contribute to the pathologies of several psychiatric disorders." (PMID 37595869, 2023).
neurodevelopmental disorder (4 papers, 2020 to 2025). A behavioral and cognitive disorder with onset during the developmental period that involves impaired or aberrant development of intellectual, motor, or social functions. "Collectively, these observations further confirm the importance of PCDH15 for normal neuronal functions and strongly support the hypothesis that PCDH15 plays a pathogenetic role in neurodevelopmental disorders." (PMID 33352832, 2020).
cancer (2 papers, 2023). A tumor composed of atypical neoplastic, often pleomorphic cells that invade other tissues. "Our observation that PCDH15 mutations are associated with specific carcinoma ecotypes is an avenue for future investigation." (PMID 38067373, 2023).
retinopathy (2 papers, 2014 to 2021). "We present one of the first genetic animal mutants for PCDH15 that displays a severe, early retinopathy and suggests that zebrafish could be a useful model for USH1F-associated retinal phenotypes." (PMID 34668518, 2021). "In this study we focused on PCDH15 (USH1F), which is associated with up to 20% of USH1 cases, to generate the first PCDH15 genetic zebrafish model displaying a clear retinopathy." (PMID 34668518, 2021). "The lack of retinal phenotypes observed in mouse models of Pcdh15 and other associated USH genes has limited our understanding of the retinopathy occurring in this disorder." (PMID 34668518, 2021).
neurological diseases (1 paper, 2023). "Further investigations are warranted to explore the interaction between PCDH15 mutations and variants reported in neurological diseases and synaptic organizers such as neurexins to test this hypothesis." (PMID 37595869, 2023). "Together, these data raise the possibility that the aberrant ALE splicing of Pcdh15 may be associated with neurological disorders." (PMID 37595869, 2023).
PCDH15 also shares sentences with these, for which no sentence is quoted: Hearing impairment (5 papers); Bardet-Biedl syndrome (3); autism (2); CHARGE syndrome (2); Ciliopathies (2); diabetes (2); genetic disorder (2); Obesity (2); Senior-Loken syndrome (2); /T cell lymphomas (1); bacterial infection (1); Brain atrophy (1); cataract (1); coloboma (1); coronary artery calcification (1); deafness autosomal recessive type 23 (1); DOORS syndrome (1); endolymphatic hydrops (1); glaucoma (1); hereditary sensory and autonomic neuropathy (1); hyperthyroidism (1); influenza (1); Joubert syndrome (1); Leber congenital amaurosis (1); leukemia (1); Macular dystrophy (1); malaria (1); Meckel syndrome (1); mental disorder (1); microphthalmia (1).
A further 12 diseases each share a sentence with PCDH15 in 1 paper.